RAC1 (Rac family small GTPase 1)
Diseases named in the same sentence as RAC1 in open-access papers (continued):
Sharing a sentence is not in itself a finding about the gene and the disease.
Cerebral ischemia (continued). "Finally, it is likely that Rac1 GTPase contributes to multiple pathological events and signaling pathways, which collectively facilitate neuronal damage and cognitive dysfunction following cerebral ischemia." (PMID 20830300, 2010). "Rac1 is also a biological regulator of NADPH oxidase and has been shown to regulate apoptosis following cerebral ischemia through regulating ROS the production." (PMID 31223330, 2019). "The purpose of the current study was to examine the regulatory and functional role of the Rho GTPase, Rac1 in NADPH oxidase activation, ROS generation and neuronal cell death/cognitive dysfunction following global cerebral ischemia in the male rat." (PMID 20830300, 2010). "It is currently unknown whether Rac1 GTPase plays an important role in NADPH oxidase activation, ROS generation and oxidative stress in the hippocampus following stroke, and whether inhibition of Rac GTPase activation might preserve cognitive function following cerebral ischemia." (PMID 20830300, 2010).
endothelial dysfunction (12 papers, 2014 to 2026). In vascular diseases, endothelial dysfunction is a systemic pathological state of the endothelium (the inner lining of blood vessels) and can be broadly defined as an imbalance between vasodilating and vasoconstricting substances produced by (or acting on) the endothelium. "To investigate whether Rac1 GTPase inhibition with LT and the associated reduction in vascular oxidative stress affects endothelial dysfunction in mice, we first studied endothelial function in atherosclerotic mice treated with LT." (PMID 34422919, 2021). "C3a:C3a-Receptor signaling drives Rac1-mediated cytoskeletal stiffening, eGC degradation, NO reduction, and leukocyte adhesion, promoting endothelial dysfunction in STEMI in both macrovascular and microvascular endothelial cells." (PMID 42047759, 2026). "We believe that our study significantly extends this evidence by demonstrating for the first time that that Rac1 also plays an important role in the development of human endothelial dysfunction." (PMID 28246076, 2017). "We evaluated the effects of pharmacological inhibition of Rac1, a small GTPase protein promoting oxidative stress, in human endothelial dysfunction." (PMID 28246076, 2017). "Overall, the data indicate that endothelial dysfunction observed in altered saphenous vein segments can be reversed by Rac1 inhibition and suggest that Rac1 plays a pivotal role in the genesis of venous endothelial dysfunction in humans." (PMID 28246076, 2017). "In order to study the role of Rac1 in the development of human endothelial dysfunction, we conducted ex vivo experiments on saphenous vein portions obtained from 85 subjects who underwent saphenectomy due to chronic venous insufficiency and/or varicose veins." (PMID 28246076, 2017). "In the present study we explored the effects of pharmacological Rac1 inhibition on human endothelial dysfunction." (PMID 28246076, 2017). "Of course, future studies are encouraged to test this hypothesis and to confirm our results, testing the efficacy of Rac1 inhibition in other models of human endothelial dysfunction, particularly in human arteries." (PMID 28246076, 2017). "However, we were able to make a direct comparison of healthy versus diseased vein tracts from the same saphenous veins, which allowed us to demonstrate that varicose veins have endothelial dysfunction and significant Rac1 activation." (PMID 28246076, 2017). "Rac1 inhibition may represent a potential therapeutic intervention to reduce human endothelial dysfunction and subsequently vascular diseases in various clinical settings." (PMID 28246076, 2017). "Future studies are warranted to understand if all these subunits contribute to Rac1‐induced endothelial dysfunction in a similar manner or whether there is a specific isoform that predominantly mediates the detrimental vascular effects of Rac1." (PMID 28246076, 2017). "Thus, the aim of this study was to evaluate for the first time the effects of pharmacological Rac1 inhibition in human endothelial dysfunction." (PMID 28246076, 2017). "Herein, we also established the recruitment of Rac1 into the signaling cascade leading to ROS generation in response to sortilin, an effect mediated by NOX2, since its deficiency prevented sortilin-induced ROS production as well as endothelial dysfunction in mouse mesenteric resistance arteries." (PMID 35104805, 2022). "Accordingly, these emerging data may have applicative/translational implications because Rac1 inhibition may represent a potential therapeutic intervention to reduce human endothelial dysfunction and subsequently vascular diseases in several clinical scenarios, particularly vein‐related diseases." (PMID 28246076, 2017). "Of note, knockdown of PKCɛ abolished sortilin-induced endothelial dysfunction in WT mouse mesenteric arteries as well as activation of PYK2 and Rac1." (PMID 35104805, 2022).
endothelial dysfunction (continued). "Therefore, inhibition of FDPS ameliorates endothelial dysfunction, such as inhibition of abnormal proliferation, in PAH, in part due to a reduction in GTP-bound active Rac1 and accompanying reduced autophagy via the PI3K/AKT/mTOR signaling pathway." (PMID 35962329, 2022).
esophageal cancer (12 papers, 2010 to 2025). A primary or metastatic malignant neoplasm involving the esophagus. "Silencing TRIP12 blocks the inhibitory effect of HACE1 on Rac1 protein degradation and esophageal cancer (ESCA) tumor growth." (PMID 40948788, 2025). "This work demonstrated that the potent anti-migratory effect of ropivacaine in esophageal cancer was mediated by attenuating the axis of Rac1/JNK/paxillin/FAK and prenylation-dependent migratory signaling pathways." (PMID 35186766, 2022). "The mechanisms of the action of local anesthetics on esophageal carcinoma cells are likely due to their ability in inhibiting Rac1, inducing mitochondrial dysfunctions, and increasing oxidative stress and damage." (PMID 32450791, 2020). "Our previous study has revealed that ropivacaine inhibited esophageal carcinoma cells via targeting Rac1." (PMID 32085741, 2020). "To investigate the mechanisms of local anesthetics’ action in esophageal carcinoma cells, we examined the activities of essential molecules involved in cell migration, such as RhoA and Rac1." (PMID 32450791, 2020). "Several genes/pathways have been implicated to esophageal cancer migration, such as Cdc42, HGF/SF, Androgen receptor, RhoA, Rac-1, and Cdc42, VEGF, HER2, PLCE1, ABCG2/V-ATPase, MMS19." (PMID 28147311, 2017). "It is therefore possible that increase in the expression of Rac1 leads to the increase in the expression of p66shc through ROS in esophageal cancers also." (PMID 20565814, 2010). "Our densitometric analysis indicated 4-6 fold higher expression of Eps897 and 3-5 fold increase in expression of Rac1 in esophageal cancers compared to adjacent normal tissue." (PMID 20565814, 2010). "In the present report, we focus on the expression pattern of p66shc and its downstream targets i.e., Eps8 and rac1 proteins in human esophageal carcinomas (one of the most common cancer worldwide)." (PMID 20565814, 2010). "The expression level of downstream targets of p66shc i.e., eps8 and rac1 was also found to be consistently higher in human esophageal carcinomas, and hence correlated positively with p66shc expression." (PMID 20565814, 2010). "Curcumin could inhibit SDF-1α-induced invasion through Rac1/PI3K/Akt signaling complexes in human esophageal carcinoma cells." (PMID 32605180, 2020). "Rac1, a key GTPase, facilitates cell migration in esophageal cancer cells." (PMID 24797725, 2014).
Insulin resistance (12 papers, 2018 to 2025). Increased resistance towards insulin, that is, diminished effectiveness of insulin in reducing blood glucose levels. "This has also been proposed by in vitro studies of muscle showing that ceramide-induced insulin resistance was associated with marked impairments in insulin-induced Rac1 activation." (PMID 31075957, 2019). "Decreased skeletal muscle Rac1 signaling has been associated with insulin resistance in insulin resistant obese and type 2 diabetic human subjects, as well as in diabetic ob/ob mice and diet-induced obese insulin resistant rodents." (PMID 31075957, 2019). "Although it is well known that obesity causes insulin resistance of skeletal muscle, it remains unclear whether Rac1-mediated signaling is indeed impaired in insulin-resistant states associated with obesity." (PMID 37511290, 2023). "Taken together, Rho GTPases, in particular Rac1 and RhoA, may be highly implicated in muscular insulin resistance and thereby contribute to metabolic dysregulation in metabolic diseases, such as type 2 diabetes." (PMID 31075957, 2019). "However, it remains obscure whether signaling cascades upstream and downstream of Rac1 in skeletal muscle are impaired by obesity that causes insulin resistance and type 2 diabetes." (PMID 37511290, 2023). "Accordingly, good evidence for lower basal p-PAK1Thr423/p-PAK2Thr402 with WHEY vs KDPWHE suggests changes to RAC1-associated cytoskeletal remodelling may be associated with the relative resistance to exercise-mediated improvement of insulin resistance seen with WHEY vs KDPWHE." (PMID 37812879, 2023). "Future research should explore therapeutic strategies targeting specific signaling pathways, such as Rac1, to mitigate the pro-metastatic effects of obesity-driven insulin resistance." (PMID 40629272, 2025). "Rac1 appears to be essential for insulin signaling in muscle glucose uptake, which implicates Rac1 in human insulin resistance and dysglycemia." (PMID 37566054, 2023). "How stimulation of Rac1‐GTP binding can be maintained during insulin resistance and if other impairment to Rac1 activation is present during insulin resistance, including altered localization, remain important questions of interest." (PMID 30592185, 2018). "Therefore, obesity may cause a decrease in the Rac1 protein level only in specific types of skeletal muscles, such as soleus and EDL muscles, which may partly account for insulin resistance in obese mice." (PMID 37511290, 2023). "However, it is plausible that other mechanisms for inducing whole-body glucose intolerance and insulin resistance in adipo-rac1-KO mice may exist, considering that the contribution of WAT to insulin-dependent alteration in the blood glucose level is not so large." (PMID 34639094, 2021). "Disturbances in the function of Rac1 signaling have been observed in insulin resistance in both human and mice, but the effects of different exercise training intensities on the expression of PAK1 and Rac1 remain sparsely characterized." (PMID 33329033, 2020). "Our findings further support the critical need for functional actin remodeling for skeletal muscle insulin action and the potential role for effectors of Rac1, such as PAK, in the development of insulin resistance." (PMID 30592185, 2018). "We instead provide evidence that attenuated PAK phosphorylation and impaired GLUT4 translocation during palmitate‐induced insulin resistance can occur independent of defects in insulin‐stimulated Rac1‐GTP binding." (PMID 30592185, 2018). "Furthermore, a lack of RAC1 is associated with insulin resistance in humans and rodents and ELMO2 and RAC1, both regulate the insulin dependent membrane translocation of the glucose transporter 4 (GLUT4) in muscle cells." (PMID 35874819, 2022). "However, in another in vitro model of insulin resistance, palmitate treatment did not impair Rac1 activity, although the phosphorylation of Rac1’s downstream target, PAK1 was reduced." (PMID 31075957, 2019).
Insulin resistance (continued). "Interestingly, in a recent study from our laboratory, we observed that lack of Rac1 in muscles from diet-induced obese mice exacerbates insulin resistance, suggesting a relevance for Rac1 in counteracting metabolic dysfunctions." (PMID 31075957, 2019).
type 2 diabetes (12 papers, 2016 to 2024). "Therefore, it is important to clarify whether the Rac1 signaling pathway is negatively affected by obesity, which causes a variety of diseases, including type 2 diabetes." (PMID 37511290, 2023). "Hyperactivation of Rac1 is observed in islets from patients and mouse models of type 2 diabetes, whereas in skeletal muscle, Rac1 signaling is diminished in insulin-resistant states in both mice and humans." (PMID 39598690, 2024). "Further in vitro and in vivo studies revealed that overexpression of dominant-negative Rac1 or treatment with a Rac1 inhibitor blocked high glucose-induced cardiomyocyte apoptosis and improved heart function in type 2 diabetic db/db mice." (PMID 28101515, 2016). "It is important to note that chronic activation of RAC1 has been found in many diseases, including cancer, neurodegenerative diseases (Parkinson’s and Alzheimer’s diseases), and cardiometabolic disorders, including type 2 diabetes." (PMID 36902173, 2023). "Interestingly, one of the main stages in the development of metabolic dysregulation of islet beta-cells in type 2 diabetes is thought to be sustained activation of RAC1." (PMID 36902173, 2023). "In addition, glucose-induced Rac1 stimulation had a role in the activation of renal MR in cultured mesangial cells, which ultimately led to the death of those cells and nephropathy in an animal model of obesity-related type 2 diabetes (T2D)." (PMID 37566054, 2023). "In particular, Klotho could act as an inhibitor of IGF-1R signaling to improve hepatic glucolipid homeostasis and lipid accumulation in Type 2 diabetes (T2D), that prompted us to determine whether IGF-1R acted as a regulator linking Klotho to RAC1." (PMID 37891556, 2023). "The link between polymorphic genes involved in redox homeostasis, such as GCLM (rs2301022), GGT7 (rs6119534, rs11546155), GSTM1 (+/del), GSTP1 (rs1695, rs1138272), RAC1 (rs7784465), and CYBB (rs5917471), and type 2 diabetes differs in overweight and normal-weight individuals." (PMID 36902173, 2023). "For example, hyperactivation of Rac1 has been demonstrable in human islets exposed to glucotoxic conditions and in islets derived from the Zucker diabetic fatty (ZDF) rat, a model of type 2 diabetes." (PMID 31075957, 2019).
cyst (11 papers, 2011 to 2026). A sac-like closed membranous structure that may be empty or contain fluid or amorphous material. "However, critical questions remain regarding RAC1 activation during cyst formation, cyst origins, and underlying molecular mechanisms." (PMID 41742835, 2026). "Rho1, together with Rac1, regulates germ cell enclosure functions via somatic cyst cells in the Drosophila testis." (PMID 32896929, 2020). "Knockdown of fat1 in zebrafish caused a decrease in the amount of active RAC1 and CDC42 available and the addition of RAC1/CD42 was partially able to rescue the cyst phenotype observed." (PMID 29502161, 2019). "EGFR-dependent Rac1 activation in SCCs is suggested to play an essential role in controlling the germline proliferation and differentiation within a cyst." (PMID 30045884, 2018). "Although the exact mechanism is unclear, the epidermal growth factor receptor (EGFR) activation in SCCs has been reported to control spermatogonial divisions within a cyst, through downstream activations of Rac1-dependent pathways." (PMID 30045884, 2018). "We confirm the relevance of this disease mechanism by showing that two different RAC1/CDC42 activators mitigate the pronephric cyst phenotype in zebrafish." (PMID 26905694, 2016). "By applying Raichu Förster Resonance Energy Transfer (FRET) biosensors to the MDCK cyst system, we recently visualized Rac1 activation during cystogenesis." (PMID 23284959, 2012). "The possibility that these cyst phenotypes resulted from impaired Rac1-activation was further assessed by overexpressing a dominant-active GFP-tagged form of Rac1 (GFP-Rac1G12V) in Itgα2- and Itgβ1-KD cells grown in collagen." (PMID 21573123, 2011). "Contrary to the prevalent hypothesis, both the somatic Rac1 and integrity of cyst enclosure appeared to be inessential for the TA regulation." (PMID 30045884, 2018). "Therefore, it is now established that Rac1 suppression at the apical membrane is required for the mature cyst to maintain its morphology." (PMID 23284959, 2012). "Furthermore, it has been reported that in 3D Matrigel culture, MDCK cells depleted of the small GTPase Arf6 form an inverted cyst, whose inversion is restored by epidermal growth factor‐elicited Rac1 activation and by expression of a constitutively active form of Rac1." (PMID 39377417, 2024). "We previously demonstrated in three-dimensional cyst cultures of Madin-Darby canine kidney (MDCK) cells that signaling by β1 integrins regulates the orientation of the apical surface, via a mechanism that depends on the activity of the small GTPase Rac1." (PMID 22815903, 2012).
endometrial cancer (11 papers, 2016 to 2025). Primary or metastatic malignant neoplasm involving the endometrium (mucous membrane that lines the endometrial cavity). "Though our mechanistic studies for tumorigenesis mainly focused on the colorectal and endometrial cancer cell line, the higher expression of activated Rac1 is also demonstrated in ovarian tumor samples harboring germline CGN c.3560C > T." (PMID 38424547, 2024). "The results suggested that DOCK1 might mediate c-Raf/ERK pathway via regulating the activity of Rac1 to involve in regulating endometrial cancer malignancy." (PMID 38438882, 2024). "For example, 100 nM of 1α,25(OH)2D3 was shown to inhibit cellular proliferation in endometrial carcinoma cells by targeting and modulating actin cytoskeleton organization via the ras-related C3 botulinum toxin substrate 1 (RAC1)/p21 protein-activated kinase 1 (PAK1) signaling pathway." (PMID 38785827, 2024). "Interestingly, Lin and co-workers recently described a NMU-NMUR2-mediated modulation of CD44 and RAC1 expression in endometrial cancer cells." (PMID 28423716, 2017). "Application of the Rac1 inhibitor NSC23766 trihydrochloride (100 μM) for 2 hours was followed by a significant increase of soluble G-actin over F-actin in human endometrial cancer Ishikawa cells (***P = 0.0006), thus mimicking the effect of LeftyA treatment (*P = 0.037)." (PMID 27404958, 2016). "Hence, DOCK1 might mediate c-Raf/ERK signaling pathway via Rac1 activation to modulate malignancy of endometrial cancer." (PMID 38438882, 2024). "Moreover, the activity of NF-κB in endometrial carcinoma promotes tumor cell migration, invasion, and metastasis via stimulation of Ras-related C3 botulinum toxin substrate 1 (Rac1), MMP-2, and MMP-9 transcription, and thus the basement membranes’ and ECM degradation, respectively." (PMID 36769226, 2023).